CXCL8 (C-X-C motif chemokine ligand 8)
Diseases named in the same sentence as CXCL8 in open-access papers (continued):
Sharing a sentence is not in itself a finding about the gene and the disease.
prostate carcinoma (273 papers, 2008 to 2026). A carcinoma that arises from epithelial cells of the prostate gland. "We have previously shown that PTEN loss selectively potentiates CXCL8 signalling in pre-clinical human and genetically engineered murine models of prostate cancer." (PMID 32743555, 2020). "A number of studies have linked higher serum levels or expression of CXCL8/IL-8 with aggressive prostate cancer." (PMID 33569050, 2020). "The IL-1α pathway target CXCL8 (IL-8) is associated with disease progression and overall survival in human prostate cancer." (PMID 29502208, 2018). "Several lines of evidence have suggested associations between IL6 and CXCL8, and prostate cancer aggressiveness, progression, and poor clinical outcome." (PMID 30473726, 2018). "From literature, CXCL8 knockdown in prostate cancer cell lines (PC-3 and DU145) was associated with decreased cell proliferation and an arrest of PC-3 cells in G1 phase of cell cycle, thus preventing their entry into S-and G2/M phases." (PMID 30108682, 2018). "The IL-1α pathway target CXCL8, which is associated with prostate cancer disease progression and reduced survival, was up-regulated in myeloid-driven tumor cells." (PMID 29502208, 2018). "We have associated increased expression and secretion of the pro-inflammatory CXC-chemokine CXCL8 with loss of PTEN function in prostate cancer cells and prostatic tissue." (PMID 24970800, 2014). "The human prostate cancer cells overexpressing CXCL8 became highly tumorigenic and metastatic with associated increased angiogenesis, whereas the cells transfected with antisense CXCL8 showed reduced growth and metastatic potential." (PMID 24971349, 2014). "Overexpression and increased activity of three specific chemokines termed CCL2, CXCL12 and CXCL8 have been strongly implicated in the progression of prostate cancer." (PMID 24970800, 2014). "We propose this chemokine cross-talk has greatest relevance to foci of PTEN-deficient prostate cancers which secrete higher levels of CXCL8 in order to trigger the induction of stromal chemokine synthesis." (PMID 24970800, 2014). "Impaired PTEN function is a genetic hallmark of aggressive prostate cancers (CaP) and is associated with increased CXCL8 expression and signaling." (PMID 24970800, 2014). "Work from our laboratory has determined that the induction of CXCL8 signaling plays an important role in sustaining the viability of PTEN-deficient prostate carcinomas." (PMID 24276377, 2013). "Furthermore, siRNA and shRNA suppression of PTEN in DU145 and 22Rv1 prostate cancer cell lines has also been shown to upregulate CXCL8 mRNA that encodes the proinflammatory chemokine interleukin 8 (IL8)." (PMID 33105713, 2020). "Elevated CXCL8 has been linked to worse overall survival in prostate cancer." (PMID 29502208, 2018). "Therefore, each of these cell types within the tumor microenvironment is potentially receptive to the increased levels of CXCL8 secreted by PTEN-deficient prostate cancer cells." (PMID 24970800, 2014). "Furthermore, loss of PTEN function concurrently increased the expression of CXCL8 receptors (CXCR1 and CXCR2), with the resulting elevated autocrine CXCL8 signaling acting to sustain the viability of these PTEN-deficient prostate cancer cells." (PMID 24970800, 2014). "Therefore, the initial objective of this study was to establish the existence of interplay between tumor-derived CXCL8 from PTEN-deficient prostate cancer cells and the potentiation of stromal-derived CCL2 and CXCL12 expression and/or signaling." (PMID 24970800, 2014). "Therefore, these initial experiments suggest that CXCL8 signaling can potentiate expression of the receptors transducing its biological activity in PTEN-deficient prostate carcinoma cells." (PMID 24970800, 2014). "Similarly, PTEN loss can also selectively upregulate the CXCL8 signaling in prostate cancer cells." (PMID 35372515, 2022).
prostate carcinoma (continued). "Previous studies have shown that C. acnes has the capability to stimulate secretion of IL6 and CXCL8 by prostate epithelial cells in vitro, and a microenvironment containing high levels of these two inflammatory mediators has been associated with prostate cancer progression." (PMID 30473726, 2018). "In prostate cancer (PCa), interleukin-8 (IL-8/CXCL8) was shown to enhance angiogenesis, proliferation, and metastasis." (PMID 39766038, 2024). "We have also shown that CXCL8 can reduce the level of intracellular ROS by inhibiting the function of GSK-3β to suppress prostate cancer cell apoptosis." (PMID 35372515, 2022). "The ability of vitamin D to reduce CXCL8 expression was demonstrated in prostate cancer cells, with the consequence of a reduction of angiogenesis, one of the CXCL8 well-known pro-tumorigenic effects." (PMID 35498406, 2022). "CXCL8 can also promote dynamic and time-dependent induction of Rho-GTPases family in prostate cancer and endothelial cells." (PMID 35372515, 2022). "Androgen receptor signaling in CAFs affects prostate cancer cell migration mediated by CXCL8 and CCL2." (PMID 35011369, 2021). "CXCL8 secreted from M2 macrophages promotes prostate tumorigenesis and proliferation of prostate cancer cells in vitro." (PMID 35011369, 2021). "Intrinsic CXCL8 signalling underpins prostate cancer cell survival through the activation of AR, HIF-1 and NF-κB transcription factors, and increases expression of anti-apoptotic proteins, including members of the Bcl family." (PMID 32743555, 2020). "For example, PC-3 prostate cancer cells overexpressing CXCL8 present rapidly tumorigenicity, highly proliferation rate, remarkably angiogenesis, and exhibit 100% incidence of lymph node metastasis." (PMID 32766720, 2020). "Elevated CXCL8 expression is observed in prostate cancer tissues compared with paired normal controls, as well as in prostate cancer cell lines, and its activation enhances their migratory and invasive potential." (PMID 32585812, 2020). "CXCL8 effects on prostate cancer metastasis are mediated mainly via its proangiogenic ability within tumors as well as its influence on EMT and these have been documented by various studies." (PMID 32585812, 2020). "In support of our findings, it has been demonstrated that CXCL8 (also known as IL-8) contributes to prostate cancer progressions such as tumorigenesis, metastasis, and chemoresistance." (PMID 32971847, 2020). "CXCL8 can significantly increase tumour vessel density in prostate cancer, which has a very strong angiopoiesis effect." (PMID 32201645, 2020). "Consistent with our results, prostate cancer-derived CXCL8 induces chemotaxis of macrophage-like THP-1 cells." (PMID 32971847, 2020). "For example, CXCL8 expression was previously shown in an in vivo study to correlate with increased angiogenesis, tumor development, and metastasis in human prostate cancer cells." (PMID 32585812, 2020). "The increase in proliferation and migration in TCM-stimulated prostate cancer cells is due to the effects of inflammatory cytokines such as IL-6 and CXCL8 in TCM, which is consistent with our previous study." (PMID 32196489, 2020). "And other study showed that DACH1 repressed CXCL6 and CXCL8 in a dose-dependent manner, and repression required the DS domain in prostate cancer." (PMID 31998654, 2019). "In the present study, we aimed to evaluate the influence of prostatic C. acnes infection on systemic levels of IL6 and CXCL8 in prostate cancer patients." (PMID 30473726, 2018). "Specifically, IL6 and CXCL8 have been extensively studied in relation to prostate cancer, and have both been proposed to play important roles in prostate cancer development and progression." (PMID 30473726, 2018). "Our data suggest that ASC recruitment to tumours, driven by CXCL1 and CXCL8, promotes prostate cancer progression." (PMID 27241286, 2016).
prostate carcinoma (continued). "Autocrine CXCL8 signaling was shown to-upregulate the expression of chemokine receptors in prostate cancer cells." (PMID 24970800, 2014). "Tumorigenesis of the human prostate cancer cell line, PC-3, was shown to be attributable, in part, to the production of CXCL8." (PMID 24971349, 2014). "While CXCL8 was unable to induce chemokine synthesis in prostate cancer cells, CXCL8 signaling did increase CXCL12 and CCL2 synthesis in prostate stromal fibroblasts and monocytes." (PMID 24970800, 2014). "Our data highlights a co-ordinated response of tumor and stromal cells to the secretion of CXCL8 from malignant prostate cancer cells." (PMID 24970800, 2014). "CXCL12-induced migration of PC3 cells and CCL2-induced proliferation of prostate cancer cells were dependent upon intrinsic CXCL8 signaling within the prostate cancer cells." (PMID 24970800, 2014). "Ultimately, the combined effect is that CXCL8 signaling increases the sensitivity of prostate cancer cells to stromal-derived chemokines." (PMID 24970800, 2014). "Serum levels of CXCL8 have been found to be markedly elevated in patients with prostate cancer and correlate with the stage of disease." (PMID 24971349, 2014). "Combined inhibition of both CXCL8 and CXCL12 signaling was more effective in inhibiting fibroblast-promoted cell motility while repression of CXCL8 attenuated CCL2-promoted proliferation of prostate cancer cells." (PMID 24970800, 2014). "Focusing on prostate cancer, the major interest of our laboratory, Veltri and colleagues initially confirmed that serum CXCL8 levels correlated with prostate cancer stage, with the greatest levels detected in patients with metastatic prostate cancer." (PMID 24276377, 2013). "We have shown that dexamethasone reduces the synthesis and secretion of CXCL8 in prostate cancer cell line models through the capacity to decrease NFκB activity in aggressive prostate cancer cells." (PMID 24276377, 2013). "Bortezomib has also been shown to inhibit proliferation and CXCL8 secretion in vitro in bladder and prostate cancer cell lines." (PMID 24276377, 2013). "IL8 is a pro-angiogenic chemokine (CXCL8) that is over-expressed in prostate cancer epithelial cells compared to normal prostate glands." (PMID 23342084, 2013). "The biochemical relationship of CXCL8 signaling and prostate cancer progression has been studied extensively in in vitro and in vivo models." (PMID 24276377, 2013). "CXCL8 signaling provides a selective resistance of metastatic prostate cancer cells to specific anti-metabolites by promoting a target-associated resistance, in addition to underpinning an evasion of treatment-induced apoptosis." (PMID 22590561, 2012). "In various other cancers, including lung cancer, prostate cancer, and squamous cell carcinoma, a similar tumor-promoting role of CXCL-8 signaling has been found." (PMID 23342280, 2012). "Interleukin-8 (IL8/CXCL8) is a key effector in prostate cancer progression and contributes to the resistance to standard chemotherapeutic drugs." (PMID 23213321, 2012). "Prostate cancer cells are subject to a pronounced autocrine CXCL8 signaling stimulus, which increases with stage of disease and is maximal in castrate-resistant disease." (PMID 22590561, 2012). "It is noteworthy that no significant CXCL8 immunoreactivity was detected in the CRC tissue, despite using similar approaches that were previously successful in assessing CXCL8 expression in prostate cancer epithelium." (PMID 21285972, 2011). "Similarly, in prostate cancer cell lines, CXCL8 contributed to increased proliferation and invasion." (PMID 35879507, 2022). "In addition, CXCL8 secreted from prostate cancer cells promotes the recruitment of adipose stromal cells from white adipose tissue (WAT), and infiltrated adipocytes affect prostate cancer progression." (PMID 32971847, 2020).
prostate carcinoma (continued). "Upregulation of CXCL8 is also a hallmark of the senescence secretory response, known as the senescence-associated secretory phenotype (SASP), which follows senescence induction and has been shown to promote therapeutic resistance in men with prostate cancer." (PMID 33105713, 2020). "For prostate cancer, CXCL8 upregulates the expression of CXCR7, which could interact with EGFR directly to induce cancer cell growth." (PMID 31304688, 2019). "CXCL8-mediated signaling can promote survival of prostate cancer cell in hypoxic environments." (PMID 30723697, 2018). "A low-grade chronic inflammation caused by prostatic C. acnes infection, including induced secretion of IL6 and CXCL8, may thus over time contribute to prostate cancer development." (PMID 30473726, 2018). "Interestingly, CXCL8 signaling increased the expression of CXCR1 and CXCR2 receptors in PTEN-deficient prostate cancer cells, suggesting that CXCL8 signaling acts in a self-sustaining capacity, to potentiate its signaling in PTEN-deficient prostate cancer." (PMID 24970800, 2014). "Furthermore, repression of CXCL8 signaling reduced the sensitivity of prostate cancer cells to these effects of CCL2." (PMID 24970800, 2014). "Our data demonstrates that tumor-derived CXCL8 acts to increase the secretion of stromal-derived chemokines which then activate the increased pool of their respective receptors expressed on the surface of prostate cancer cells." (PMID 24970800, 2014). "Co-culture experiments were conducted to examine whether CXCL8-induced increases in stromal cell-derived CXCL12 expression could potentiate prostate cancer cell migration." (PMID 24970800, 2014). "Similarly, overexpression of CXCL8 in prostate cancer cell lines resulted in MMP-9 upregulation and increased invasiveness." (PMID 24971349, 2014). "Consistent with our earlier results indicating that CXCL8 signaling up-regulated CCR2 and CXCR4 expression in prostate cancer cells, we observed that the reduction in autocrine CXCL8 expression resulted in a significant decrease in CCR2 and CXCR4 mRNA expression in PC3-120 cells." (PMID 24970800, 2014). "Increased expression and activity of CCL2 and CXCL12 has been reported in both the localized prostate cancer and within the microenvironment of bone metastases, while prior work from our own group has confirmed elevated CXCL8 expression in human prostate cancer tissue." (PMID 24970800, 2014). "Both c-FLIP isoforms, c-FLIPL and c-FLIPS, were up-regulated by CXCL8 in prostate cancer cells." (PMID 24276377, 2013). "Inhibition of CXCL8 signaling or down-regulation of c-FLIP sensitized prostate cancer cells to tumor necrosis factor-related apoptosis-inducing ligand (TRAIL)- and chemotherapy (oxaliplatin)-induced apoptosis in both androgen-dependent (LNCaP) and androgen-independent (PC3) cell lines." (PMID 24276377, 2013). "CXCL8 promotes progression to castrate-resistance through ligand-independent activation of the androgen receptor (AR) and induces the proliferation of metastatic prostate cancer cells." (PMID 22590561, 2012). "In addition to underpinning resistance to AR-targeted therapy, induction of CXCL8 signalling modulates the sensitivity of prostate cancer cells to several novel molecular targeted therapies and chemotherapeutic agents, including oxaliplatin that induces DNA double-strand breaks in CaP cells." (PMID 32743555, 2020). "Furthermore, CXCL8 signaling also increased the expression of CXCR4 and CXCR7 (the receptors mediating the biological activity of CXCL12) and CCR2 (a receptor activated by the ligand CCL2) in both PTEN-expressing and PTEN-deficient prostate cancer cells." (PMID 24970800, 2014). "In this study, we report a co-operative role between CXCL8 and stromal-derived chemokines, establishing a multi-faceted chemokine cross-talk between PTEN-deficient tumor and stroma that sustains the proliferation, migration and invasion of these aggressive prostate cancer cells." (PMID 24970800, 2014).
prostate carcinoma (continued). "Moreover, the release of CXCL8 from PTEN-depleted prostate cancer cells may act in a paracrine manner to increase the expression and secretion of CCL2 and CXCL12 from neighboring stromal cells." (PMID 24970800, 2014). "Since we have now shown that CXCL8 signaling modulates the sensitivity of metastatic prostate cancer cells to both 5-FU and oxaliplatin, expression of this chemokine could be used as a guide to assist in predicting a patient's response to an oxaliplatin/5-FU combination." (PMID 22590561, 2012). "Furthermore, we have shown that stress-induced CXCL8 signaling attenuates the sensitivity of prostate cancer cells to undergo apoptosis in response to DNA-damaging agents, Hsp90-directed inhibitors, death receptor agonists (TRAIL) and AR-targeted therapeutics such as bicalutimide (Casodex)." (PMID 22590561, 2012). "Recently, several chemokines, including CXCL8 and its receptors (CXCR1 and CXCR2), have been shown to impact the development and progression of prostate cancer." (PMID 39766038, 2024). "For example, we showed that the expression of CXCL6 and CXCL8, the functional homologs of mouse Cxcl5, are both inversely correlated with that of FOXF2 in human prostate cancer specimens." (PMID 36369237, 2022). "We found that the down-regulation of SFMBT2 promotes the up-regulation of CXCL8, CCL2, CXCL10, and CCL20 expression in prostate cancer cells, resulting in elevated infiltration of preadipocytes and TAMs." (PMID 32971847, 2020). "In prostate cancer cell lines, distant metastases and PDX lines, detectable levels of CXCL8 have been observed." (PMID 32585812, 2020). "During the early phase of metastasis, cytokines such as TGFβ, IL-6, CXCL8, IL-7, CXCL16, and CX3CL1 induce EMT in prostate cancer cells and transforms them to exhibit higher migratory and invasive potentials." (PMID 32585812, 2020). "We also found that the up-regulation of CXCL8, CCL2, CXCL10, and CCL20 expression is dependent on NF-κB activation in prostate cancer cells expressing a low level of SFMBT2." (PMID 32971847, 2020). "Immunohistochemical analysis of human normal and prostate cancer tissue array consistently demonstrated the increased expression of CXCL8, CCL2, CXCL10, and CCL20 in prostate cancer tissues." (PMID 32971847, 2020). "Expression levels of CXCL8, CCL2, CXCL10, and CCL20 in prostate cancer with Gleason scores of ≥8 were higher than those with Gleason scores of ≤7." (PMID 32971847, 2020). "Metastatic prostate cancer cell lines demonstrate increased gene expression of proangiogenic cytokines VEGF, CXCL8, and TGFβ." (PMID 32585812, 2020). "Our analysis indicated the high expression of CXCL8, CCL2, CXCL10, and CCL20 in prostate cancer tissues expressing a low expression level of SFMBT2, which is correlated with high Gleason scores." (PMID 32971847, 2020). "We found that the down-regulation of SFMBT2 promotes the infiltration of preadipocytes and TAMs through up-regulation of CXCL8, CCL2, CXCL10, and CCL20 expression in prostate cancer." (PMID 32971847, 2020). "cIAP1 is an anti-apoptotic protein that is upregulated in prostate cancer cells following CXCL8-mediated TAM infiltration, and cIAP1 inhibition has been shown to be effective in PTEN-depleted prostate cancer cells in vitro." (PMID 33105713, 2020). "As with the expression level of CXCL8, CCL2, CXCL10, and CCL20, the number of Pref-1 or CD29 positive cells was increased in prostate cancer tissues with high Gleason scores of ≥8." (PMID 32971847, 2020). "Expression of CXCL8, CCL2, CXCL10, and CCL20 is dependent on NF-κB activation in prostate cancer cells expressing low levels of SFMBT2." (PMID 32971847, 2020). "Expression of CXCL8, CCL2, CXCL10, and CCL20 was also elevated in prostate cancer patients having a higher Gleason score (≥8), which had substantially lower SFMBT2 expression." (PMID 32971847, 2020).